TRIM68 (tripartite motif containing 68)
Description:
Functions as a ubiquitin E3 ligase. Acts as a coactivator of androgen receptor (AR) depending on its ubiquitin ligase activity.
Synonyms: SS-56; GC109; RNF137; SS56; FLJ10369
Tractability: PROTAC: UniProt records ubiquitination sites on it; ubiquitination databases record sites on it.
Gene: Protein-coding gene on chromosome 11 (4,598,672 to 4,608,231, reverse strand). Ensembl gene ENSG00000167333.
Subcellular location: Cytoplasm, perinuclear region; Nucleus
Subcellular location (Human Protein Atlas): Cytosol; Nucleoplasm
Pathways (Reactome):
Immune System: Interferon gamma signaling
Gene Ontology:
Molecular function: histone acetyltransferase binding; identical protein binding; nuclear androgen receptor binding; protein binding; ubiquitin-protein transferase activity; ubiquitin protein ligase activity; zinc ion binding
Biological process: protein autoubiquitination; regulation of androgen receptor signaling pathway; innate immune response; regulation of gene expression; protein ubiquitination
Cellular component: cytoplasm; cytosol; nucleoplasm; nucleus; perinuclear region of cytoplasm
Genetic constraint (gnomAD): Loss-of-function variants: 40 observed, 49.61 expected, observed/expected ratio (o/e) 0.81, 90% interval 0.62 to 1.05. The upper end of that interval is the gene's LOEUF score, 1.05, which puts it in group 4 of 6, group 1 being the genes least tolerant of losing a copy. Missense variants: 632 observed, 635.84 expected, observed/expected ratio (o/e) 0.99, 90% interval 0.93 to 1.06. Synonymous variants: 225 observed, 237.57 expected, observed/expected ratio (o/e) 0.95, 90% interval 0.85 to 1.06.
Homologues: Orthologues: chimpanzee TRIM68 (99% identical), macaque TRIM68 (98% identical), dog TRIM68 (89% identical), pig TRIM68 (85% identical), mouse Trim68 (78% identical), rat Trim68 (77% identical). Paralogues in human: TRIM6 (38% identical), TRIM22 (35% identical), TRIM5 (34% identical), TRIM34 (34% identical), TRIM38 (32% identical), TRIM60 (32% identical), TRIM11 (32% identical), TRIM58 (32% identical), TRIM21 (32% identical), TRIM75 (32% identical), TRIM27 (30% identical), TRIM39 (30% identical), and 68 more.
Diseases named in the same sentence as TRIM68 in open-access papers:
TRIM68 is named in the same sentence as 13 diseases in open-access papers, as found by Europe PMC text mining. Sharing a sentence is not in itself a finding about the gene and the disease. The quoted sentences say what the papers report.
prostate carcinoma (9 papers, 2014 to 2025). A carcinoma that arises from epithelial cells of the prostate gland. "With regard to TRIM68, there have been many studies showing that this gene is particularly strongly associated with cancer, especially in prostate cancer." (PMID 33968741, 2021). "Tripartite Motif Containing 68 (TRIM68), a protein-coding gene, is associated with TRIM68 in diseases, including systemic lupus erythematosus and prostate cancer." (PMID 33968741, 2021). "This in turn results in the increased expression of TRIM68 and PGK-1 and these genes are associated with the progression of prostate cancer." (PMID 25647662, 2015). "For example, multiple deubiquitinating enzymes have been identified which influence AR signaling in both cytoplasm and nucleus including TRIM68 which is specifically upregulated in prostate cancer and influences AR stability." (PMID 24922532, 2014). "Previous literature indicated that YTHDF1 could mediate the m6A modification on TRIM68 to accelerate cellular viability, migration and invasion of prostate cancer." (PMID 39557826, 2024). "miR-1256 directly targets TRIM68 and contributes to the suppression of prostate cancer progression." (PMID 31371702, 2019). "Additionally, TRIM68 was also significantly up-regulated in human prostate cancers and found to play an important role in prostate cancer progression." (PMID 26799420, 2016). "Finally TRIM19, TRIM25, and TRIM68, by regulating the activation of nuclear and hormone receptors, play a key role in the progression of leukaemia, as well as the development of breast and prostate cancer." (PMID 26077989, 2015). "TRIM68 interacts with coactivators of AR such as TIP60 and p300 to mediate AR transcription in prostate cancer." (PMID 40723250, 2025). "Demethylation of these promoters leads to the decrease in expression of TRIM68 and PGK1 in prostate cancer cells, whilst methylation of the promoter of miRNA-29a led to increased expression of Myeloid cell leukemia sequence 1 (Mcl-1) which blocks apoptosis and supports cell survival in lymphoma." (PMID 25647662, 2015).
osteosarcoma (2 papers, 2021). A usually aggressive malignant bone-forming mesenchymal neoplasm, predominantly affecting adolescents and young adults. "All evidence from our study demonstrates that TRIM68, PIKFYVE, and DYNLL2 are high-risk genes involved in the development of osteosarcoma and can be used as biomarkers for predicting the prognosis of osteosarcoma." (PMID 33968741, 2021). "TRIM68, PIKFYVE, and DYNLL2 are high-risk genes involved in the development of osteosarcoma and can be used as possible biomarkers for predicting the prognosis of osteosarcoma." (PMID 33968741, 2021). "The TRIM68, PIKFYVE, and DYNLL2 genes can be used as biomarkers for predicting the prognosis of osteosarcoma." (PMID 33968741, 2021). "The expressions of TRIM68, PIKFYVE, and DYNLL2 were higher in the osteosarcoma cells compared to the control cells." (PMID 33968741, 2021).
autoimmune disease (1 paper, 2014). A disorder resulting from loss of function or tissue destruction of an organ or multiple organs, arising from humoral or cellular immune responses of the individual to their own tissue constituents. "Interestingly, both TRIM68 and TRIM21 are known autoantigens in SLE and primary Sjögrens syndrome (pSS), both autoimmune diseases associated with a high level of circulating type I IFN and an IFN-stimulated gene (ISG) signature." (PMID 24999993, 2014).
breast carcinoma (1 paper, 2020). "PE‐Lap (FBP1, ITGA11, TRIM68, BCAT1, ZNF780A, UTP20 and GRB7) predicted outcomes of breast cancer patients treated with lapatinib." (PMID 34766125, 2020).
colorectal cancer (1 paper, 2022). A primary or metastatic malignant neoplasm that affects the colon or rectum. "Depletion of TRIM68 can inhibit colorectal cancer cell proliferation." (PMID 35928444, 2022).
Obesity (1 paper, 2021). Accumulation of substantial excess body fat. "TRIM68 variants have been associated with early onset obesity and is upregulated following aerobic exercise." (PMID 33985508, 2021).
tumor (3 papers, 2022 to 2025). "The results showed that the tumor volume decreased significantly after YTHDF1 or TRIM68 knockdown, while overexpression of TRIM68 on the basis of YTHDF1 knockdown could promote tumor growth." (PMID 38042806, 2023). "DCC is considered a tumor suppressor; downregulation of TRIM9 and TRIM68 in BC may lead to changes in BC, although we did not see the correlation in the mRNA level (Spearman coefficient r = 0.022, 0.043)." (PMID 35928444, 2022).
TRIM68 also shares sentences with these, for which no sentence is quoted: cancer (1 paper); leukaemia (1); melanoma (1); myeloid neoplasm (1); primary Sjögrens syndrome (1); systemic lupus erythematosus (1).